AGK (acylglycerol kinase)
Diseases named in the same sentence as AGK in open-access papers (continued):
Sharing a sentence is not in itself a finding about the gene and the disease.
gastric cancer (continued). "Interestingly, we found that the AGK mRNA and protein levels were low in YAP1 deficient MKN‐45 cells, while YAP1‐expressing gastric cancer cell lines had higher AGK expression compared with GES‐1 cells." (PMID 32827244, 2020). "However, the TCGA‐STAD database data showed that the level of AGK mRNA was dramatically higher in gastric cancer tissue than in normal tissues." (PMID 32827244, 2020). "Future studies should assess whether the targeting of AGK expression or activity could be a therapeutic target for the control of gastric cancer progression." (PMID 32827244, 2020). "However, knockdown of AGK expression showed the opposite results in gastric cancer cells in vitro and in nude mouse tumour cell xenograft growth." (PMID 32827244, 2020). "In addition, we compared the levels of AGK mRNA and protein expression in five gastric cancer cell lines (MKN‐45, HGC‐27, SGC‐7901, BGC‐823 and MGC‐803) and one immortal gastric epithelial cell line (GES‐1)." (PMID 32827244, 2020). "This indicated that YAP1 might play important roles in the mediation of the effects of AGK in gastric cancer cells." (PMID 32827244, 2020). "We then assessed the interaction of AGK and Hippo‐YAP1 pathway in gastric cancer cells and found that AGK overexpression was able to up‐regulate level of YAP1 and CTGF proteins, but lead to a down‐regulation of the level of LATS1/2 and p‐YAP without changing in MST1/2 levels." (PMID 32827244, 2020). "Additionally, our study also delineated the feedback regulation between AGK and the Hippo pathway, which will contribute to a better understanding of the molecular mechanisms of AGK functions in gastric cancer." (PMID 32827244, 2020). "Future studies will further evaluate whether detection of AGK expression serves as a marker for early gastric cancer diagnosis or prediction of prognosis." (PMID 32827244, 2020). "We then assessed the effect of AGK overexpression and knockdown on gastric cancer viability." (PMID 32827244, 2020). "Now, our group is further investigating the regulation and functions of AGK and YAP1 gene pathways in gastric cancer development and progression." (PMID 32827244, 2020). "At the molecular level, the effect of AGK might link to a suppression of the Hippo pathway and a subsequent boost of YAP1/TEADs transcription activity in gastric cancer cells." (PMID 32827244, 2020). "Furthermore, we treated gastric cancer cells with verteporfin or metformin, the YAP inhibitors, for 48 hours, and found that verteporfin and metformin dose‐dependently down‐regulated the level of AGK protein in BGC‐823 and HGC‐27 cells." (PMID 32827244, 2020). "Our findings suggest that AGK is not only a novel target of the Hippo‐YAP1/TEADs pathway but also a repressor of the Hippo pathway; thus, acting as a stimulator of the transcription activity of YAP1/TEADs to form a positive feedback circuit in gastric cancer cells." (PMID 32827244, 2020). "We also demonstrated that AGK is a novel transcription target gene of YAP1/TEADs and is able to induce YAP1/TEADs transcription activity through the inactivation of the Hippo pathway to provide a positive feedback loop of YAP1 interaction with AGK in gastric cancer cells." (PMID 32827244, 2020).
lung carcinoma (3 papers, 2021 to 2025). "Lung cancer patients show secondary resistance to EGFR TKIs due to acquired AGK/BRAF fusion, which suggests that AGK is involved in some acquired tumor resistance, but the specific AGK mechanism in this context needs to be clarified." (PMID 34368119, 2021). "For example, an expected EML4-ALK fusion and an unexpected AGK-BRAF fusion was detected in a lung cancer sample harboring a known EML4-ALK fusion at Laboratory A during the TST170 validation and was confirmed by orthogonal testing with a different NGS assay." (PMID 34093633, 2021).
nasopharyngeal carcinoma (3 papers, 2016 to 2025). A carcinoma arising from the nasopharyngeal epithelium. "AGK was also considered to be a promoter of resistance to paclitaxel in nasopharyngeal carcinomas and this chemoresistance properties which eventually mediate tumor growth and metastasis is facilitated by overexpressed FOXM1 via JAK2/STAT3 signaling pathway." (PMID 40176914, 2025). "This study aimed to investigate the expression and clinicopathological significance of AGK in nasopharyngeal carcinoma (NPC)." (PMID 26443540, 2016).
ovarian carcinoma (3 papers, 2014 to 2025). A malignant neoplasm originating from the surface ovarian epithelium. "Tissue analysis of ovarian cancer patients confirmed that acylglycerol kinase promotes chemotherapy resistance in epithelial ovarian cancer through interaction with ribosomal protein L39." (PMID 40438494, 2025). "We also determined the prognostic value of AGK in ovarian cancer using a Kaplan-Meier plotter." (PMID 35934718, 2022). "We analyzed the prognostic value of RPL39 in patients with ovarian cancer, and found that the overexpression of RPL39 protein in 1074 patients with EOC was associated with a shorter OS than that in the 361 of those with a lower AGK protein expression (HR = 1.31, Logrank P = 0.00034)." (PMID 35934718, 2022).
clear cell renal cell carcinoma (2 papers, 2024 to 2025). "ZDHHC2 mediates AGK palmitoylation, promoting the translocation of AGK into the PM and activation of the PI3K-AKT-mTOR signaling pathway in clear cell renal cell carcinoma." (PMID 40814339, 2025).
colorectal cancer (2 papers, 2024). A primary or metastatic malignant neoplasm that affects the colon or rectum. "The AGK gene encodes a mitochondrial membrane protein involved in lipid/glycerolipid metabolism and oncogenic MAPK signaling, and its higher expression in colorectal cancer tissues also promotes cancer development." (PMID 38782890, 2024).
glioblastoma (2 papers, 2022 to 2023). The most malignant astrocytic tumor (WHO grade IV). "Interestingly, a broad range of actionable fusion genes were identified in this cohort of glioblastomas including EGFR-SEPT, EFGR intragenic recombination, FGFR3-TACC3, PTPRZ1-MET, CAPZA2-MET, METex14 skipping, AGK-BRAF, EGFR Viii, TBLXR1-PIK3CA and FIP1L1-PDGFRA." (PMID 35324914, 2022).
glioma (2 papers, 2022). A benign or malignant brain and spinal cord tumor that arises from glial cells (astrocytes, oligodendrocytes, ependymal cells). "In glioma, the expression level of AGK was identified as an independent prognostic factor and associated with the poor prognosis." (PMID 35280808, 2022). "AGK is markedly overexpressed in glioma and might play an important role in glioma development and progression." (PMID 36180956, 2022).
lung adenocarcinoma (2 papers, 2020 to 2025). A carcinoma that arises from the lung and is characterized by the presence of malignant glandular epithelial cells. "Post‐therapy specimens demonstrated PD‐L1 heterogeneity and an acyl glycerol kinase to B‐rapidly accelerated fibrosarcoma (AGK‐BRAF) fusion in a patient with an EML4‐ALK–positive lung adenocarcinoma as a potential resistance mechanism to ALK inhibitor therapy." (PMID 31747139, 2020).
Mitochondrial myopathy (2 papers, 2021 to 2022). "Among the patients whose biopsy was indicative of a mitochondrial myopathy, we reached seven genetic diagnoses including one case with mutation in mtDNA (T8993C), AGK (two cases), TSEN54 (one case), EARS (one case), TSFM (one case), and NARS2 (one case)." (PMID 34675869, 2021).
oral squamous cell carcinoma (2 papers, 2016 to 2020). "A previous study demonstrated that AGK can regulate the cell cycle of oral squamous cell carcinoma cells." (PMID 31900208, 2020). "Recently, AGK is reported to promote cell proliferation and cell cycle progression in oral squamous cell carcinoma." (PMID 26443540, 2016). "AGK can regulate the cell cycle in oral squamous cell carcinoma cells." (PMID 31900208, 2020).
Cirrhosis (1 paper, 2014). A chronic disorder of the liver in which liver tissue becomes scarred and is partially replaced by regenerative nodules and fibrotic tissue resulting in loss of liver function. "However, the biological role of AGK in cirrhosis and its relationship with hepatocarcinogenesis in cirrhotic tissues require further investigation." (PMID 25474138, 2014). "Interestingly, the expression of AGK sequentially increased in healthy liver, cirrhosis tissues and HCC, suggesting that AGK may play a crucial role in the pathogenesis of HCC." (PMID 25474138, 2014).
Cognitive impairment (1 paper, 2022). Abnormal cognition is characterized by deficits in thinking, reasoning, or remembering. "Several lines of evidence have shown that Sirt2 inhibitor (AGK-2 and AK-7) injection in AD-like mouse models decreased Aβ generation by reducing BACE1 levels, thus leading to an amelioration of cognitive impairment." (PMID 35701718, 2022).
colon cancer (1 paper, 2024). "Interestingly, the boundary of TAD containing the acylglycerol kinase (AGK) gene in colon cancer tissues was more spatially folded, resulting in an increased density of active regulatory elements in the surrounding region." (PMID 38782890, 2024).
diabetes (1 paper, 2014). "AGK expression in the vitreous samples from patients with PDR was upregulated by about 2.73-fold as compared to the vitreous samples from control patients without diabetes." (PMID 25496321, 2014). "Western blot analysis was used to quantify the expression levels of PLA1A, PLA2, AGK, S1PR1, SPL and 5-lipoxygenase in vitreous fluid samples from patients with PDR (n = 16) and control patients without diabetes (n = 16)." (PMID 25496321, 2014). "We demonstrated that PLA1A, AGK, S1PR1 and SPL were detected in all vitreous fluid samples from patients with PDR and control patients without diabetes." (PMID 25496321, 2014).
fatty acid metabolism disorder (1 paper, 2022). "Furthermore, AGK is mainly located in the mitochondria of hepatocytes, and the kinase deficiency induces mitochondrial crista disappearance, mitochondrial oxidative phosphorylation damage, and fatty acid metabolism disorder in hepatocytes." (PMID 35547757, 2022).
fibrosarcoma (1 paper, 2020). A malignant mesenchymal fibroblastic neoplasm affecting the soft tissue and bone. "Genetic testing of the postmortem lung tumor and metastatic lymph node tissues revealed not only the EML4‐ALK fusion but also a previously unknown in‐frame acyl glycerol kinase to B‐rapidly accelerated fibrosarcoma (AGK‐BRAF) gene fusion." (PMID 31747139, 2020).
lymph node metastasis (1 paper, 2016). "High AGK expression was associated with lymph node metastasis (P < 0.001; chi-squared test) and was an independent predicted factor for lymph node metastasis in NPC (P = 0.032; multivariate logistic analysis)." (PMID 26443540, 2016). "High AGK expression was associated with poorer survival and lymph node metastasis in patients with NPC." (PMID 26443540, 2016). "AGK is overexpressed and associated with disease progression and lymph node metastasis in NPC." (PMID 26443540, 2016). "Therefore, we evaluated the association between the expression of AGK and lymph node metastasis." (PMID 26443540, 2016). "In the subgroup of patients with lymph node metastasis, patients with higher levels of AGK expression had a shorter survival time compared to those with lower AGK expression." (PMID 26443540, 2016). "Multivariate logistic analysis revealed that AGK may also represent an independent biomarker for lymph node metastasis in NPC." (PMID 26443540, 2016). "Additionally, high expression of AGK was an independent prognostic factor for lymph node metastasis in NPC." (PMID 26443540, 2016). "Furthermore, in the subgroup of patients with lymph node metastasis, patients with higher levels of AGK expression had a shorter survival time compared to those with lower AGK expression." (PMID 26443540, 2016). "In our study, there was significant difference between the immunohistochemical status of AGK protein expression in patients with lymph node metastasis and patients without lymph node metastasis (P < 0.001; chi-squared test)." (PMID 26443540, 2016). "In this study, we observed significantly higher AGK protein expression in patients with NPC with lymph node metastasis compared to those without lymph node metastasis." (PMID 26443540, 2016).
mood disorder (1 paper, 2015). A cognitive disorder a disturbance in which the person's mood is hypothesized to be the main underlying feature. "The most significant association in the mood disorder analyses was in the prion+ vs controls analysis for a SNP lying within the acylglycerol kinase (AGK) gene (rs7789850; P=2.16 × 10−6, OR=4.6)." (PMID 25897833, 2015).
mtDNA depletion syndrome (1 paper, 2019). "Notably, in the study of SIL1 negative, atypical MSS patients, one patient was ultimately diagnosed with an AGK-related mtDNA depletion syndrome." (PMID 31463572, 2019).
parotid gland carcinoma (1 paper, 2026). A primary or metastatic malignant neoplasm involving the parotid gland. "The “Genetic Biomarkers” view of the KC integrates all alteration types affecting a gene of interest, e.g., BRAF in a 59-year-old male with parotid gland carcinoma harboring a previously unknown AGK::BRAF fusion that resulted from a genomic inversion reported as a structural variant (SV)." (PMID 41554728, 2026).
steatosis (1 paper, 2022). Increased lipid within the cytoplasm of cells. "The data also revealed that AGK-deficient mice developed more severe NASH phenotypes than Agkf/f mice after CDAHFD feeding: higher levels of serum ALT and AST, more severe lipid accumulation and fibrosis, and greater steatosis." (PMID 35547757, 2022).
Thrombocytopenia (1 paper, 2021). A reduction in the number of circulating thrombocytes. "The most recent research declared that megakaryocyte/platelet-specific AGK-deficient mice show thrombocytopenia and splenomegaly." (PMID 34368119, 2021).
triple-negative breast carcinoma (1 paper, 2024). An invasive breast carcinoma which is negative for expression of estrogen receptor (ER), progesterone receptor (PR), and human epidermal growth factor receptor 2 (HER2). "This discrepancy may be attributed to varying expression levels of AGK protein in these two cell lines or could be associated with the heightened activation of the PI3K/AKT/mTOR signaling pathway in triple-negative breast cancer." (PMID 39594764, 2024). "Considering that the role of AGK as a therapeutic target in triple-negative breast cancer has not been definitively established, we employed siRNA to knock down the AGK gene in the SK-BR-3 and MDA-MB-231 cell lines." (PMID 39594764, 2024). "However, this study did not assess the effects of targeting AGK in triple-negative breast cancer." (PMID 39594764, 2024).
tumor (24 papers, 2014 to 2025). "AGK is involved in the regulation of various signaling pathways and transcription factors, and its increased expression in tumor cells is associated with poor prognosis in multiple cancers." (PMID 40568577, 2025). "In this preclinical study, we set out to investigate the impact of tovorafenib alone or in combination with MEK inhibitor pimasertib in adult or pediatric tumor models harboring either an AGK::BRAF fusion or an NF1-LOF mutation." (PMID 40111124, 2025). "Together, these data demonstrated that AGK-deficient macrophages inhibit tumor growth through their activation of T cells." (PMID 39816692, 2025). "The tumor-promoting mechanisms associated with AGK are primarily linked to its protein kinase activities." (PMID 39594764, 2024). "Univariate analysis revealed that tumor stage, peritoneal cytology, the volume of ascites and the overexpression of AGK were associated with PFS and OS." (PMID 35934718, 2022). "An AGK‐BRAF fusion was newly identified in tumor from a donor with a known echinoderm microtubule‐associated protein‐like 4 to anaplastic lymphoma kinase (EML4‐ALK) fusion and history of anaplastic lymphoma kinase (ALK) inhibitor therapy." (PMID 31747139, 2020). "Previous studies have shown that AGK is overexpressed in various types of human cancer and is associated with tumour cell proliferation and tumorigenicity." (PMID 32827244, 2020). "We found that AGK deficiency in macrophages stimulated a transformation towards an anti-tumorigenic phenotype, leading to enhanced T cell infiltration, increased stemness, and improved anti-tumor activity." (PMID 39816692, 2025). "In addition, blockade of IFNAR signaling eliminated the impact of AGK deficiency in macrophages on the percentages and numbers of tumor-infiltrating T cells, CD107a+CD8+ T cells, and PD1+Tcf1+Tim3-CD8+ cells." (PMID 39816692, 2025). "However, we repeated our experiments in YAP1‐deficient MKN‐45 cells and found that, in these cells, AGK only mildly regulated tumour cell proliferation." (PMID 32827244, 2020). "We detected the exhaustion status (PD1+Tim3+) of CD8+ tumor-infiltrating T cells in B16-OVA tumor-bearing mice and found that AGK deficiency significantly downregulated PD1 and TIM3 expression on CD8+ T cells." (PMID 39816692, 2025). "Together, these data demonstrated that AGK in macrophages suppresses the maturation of TAMs and host anti-tumor activity in vivo." (PMID 39816692, 2025). "Our data demonstrate that the genetic deletion of AGK in macrophages enhanced their anti-tumoral capabilities by driving a type I IFN response that in turn increase anti-tumor T cell responses." (PMID 39816692, 2025). "miR-194 was found to inhibit cellular proliferation in OSCC by suppressing acylglycerol kinase (AGK) expression via the PI3K/AKT/FoxO3a signaling pathway acting as a tumor suppressor." (PMID 40176914, 2025). "Next, to address the role of AGK in macrophages in tumor development, we crossed Agkfl/fl mice with lysozyme-Cre (LyzCre) mice to generate Agkfl/fl;LyzCre mice (hereafter, AgkcKO)." (PMID 39816692, 2025). "Further analyses with a multivariate model showed that tumor stage (P = 0.011), optimal cytoreductive surgery (P = 0.003) and an upregulated AGK (P = 0.036) were independent prognostic factors for a poor PFS." (PMID 35934718, 2022). "In human DLBCL tumor tissues, the expression of AGK inversely correlated with BCL-2 expression, as well as the amounts of nuclear FOXO1." (PMID 35910796, 2022). "In the present study, we found that AGK enhanced the tumor sphere potential and the expression of stemness genes increased, such as ALDH1, SOX2, OCT4, NANOG, LIN28 and EOC stemness gene CD44." (PMID 35934718, 2022). "We next assessed the effect of AGK expression on sphere formation, an index of self-renewal ability, using tumor sphere formation assay." (PMID 35934718, 2022).